TLR7 (toll like receptor 7)
Diseases named in the same sentence as TLR7 in open-access papers (continued):
Sharing a sentence is not in itself a finding about the gene and the disease.
cancer (continued). "Nevertheless, it described variable TLR7 expression patterns when comparing between normal, dysplastic, and carcinoma tissues." (PMID 31238894, 2019). "Previous studies showed that TLR7/8 agonists, including R848, preferentially induced mMDSC isolated from healthy donors or cancer patients to mature into tumoricidal macrophage with the ability to produce pro-inflammatory cytokines." (PMID 29632539, 2018). "This suggests a possible interaction between CR42-24 and TLR7, and a TLR7-mediated anti-cancer effect of the compound." (PMID 29462934, 2018). "We also employed a cell line-based experiment to demonstrate the possible interaction between the compound and TLR7, by studying the effect that CR-24-42 has on cancer cells carrying either a wild-type or a mutant TLR7 gene, respectively." (PMID 29462934, 2018). "The binding to the TLR7 was further assessed by introducing genetic transformations in the TLR7 gene in cancer cell lines and exposing them to the compound." (PMID 29462934, 2018). "Recently, different TLR7-targeting small molecules were developed as immune response modifiers for anti-cancer and anti-viral therapy." (PMID 29462934, 2018). "Synthetic substances, such as resiquimod (R848, ligand for TLR7/8), have been extensively studied either as single agents in experimental cancer models or as vaccine adjuvants in clinical trials." (PMID 29190907, 2017). "Enhanced colorectal tumor expression of TLR7/8 colocalized with the cancer stem cell marker CD133 and correlated with reduced overall survival." (PMID 27941651, 2016). "Both miR-21 and miR29a can act within cancer cells or can be delivered from cancer cells to macrophages by microvesicles and can subsequently bind intracellular TLR7 or TLR8." (PMID 25743773, 2015). "TLR7/TLR8 agonists are less developed as adjuvants but are already used with success in topical cancer immunotherapy." (PMID 26344622, 2014). "Based on our results, we concluded that IMQ activates the STAT3 and PI3K/Akt pathways to increase HIF-1α expression at both the transcriptional and translational levels in TLR7/8-negative cancer cells." (PMID 24658058, 2014). "In our study, the TLR7 gene was down-regulated in cancer patients according to the RT-PCR results, and partially returned to normal levels after combination chemotherapy." (PMID 23451142, 2013). "The cancer specificity of TLR agonists consists of the preferential attraction of TLR-7 expressing pDCs to chronically inflamed tissues and their enhanced recruitment." (PMID 17222352, 2007). "4T1 cancer cells were treated with the TLR7/8 agonist R848 and doxorubicin for a duration of 48 h." (PMID 41550509, 2026). "TLR7/8 agonists also modulate immunosuppressive myeloid populations and improve the efficacy of immune checkpoint inhibitors, underscoring their translational relevance in cancer immunotherapy." (PMID 41228373, 2025). "Despite their promise, FDA-approved cancer vaccines incorporating TLR7/8 agonists remain limited." (PMID 41228373, 2025). "In the context of cancer, HLA-DR and TLR7 play distinct but interrelated roles." (PMID 40853959, 2025). "Our findings have translational relevance by suggesting future clinical investigation of the TRAIL innate immune pathway, CCL22, and TLR7 in toxicity of radiation or other cancer therapeutics and in other inflammatory lung or skin conditions, and have implications for radiation countermeasures." (PMID 39808500, 2025). "Therefore, the novel therapeutic strategy of the combination with IQM, a TLR‐7 agonist, and nivolumab, an anti‐PD‐1 mAb, efficiently rotates the cancer immune cycle by affecting the second and seventh steps of the cancer immunity cycle, respectively." (PMID 40371846, 2025). "TLR7 agonists can be effective in potentiating antitumor effects, and there is growing evidence that these agonists can directly stimulate antitumor responses in a variety of cancers when used in combination with standard therapies." (PMID 39857735, 2025).
cancer (continued). "Using TLR7/8 agonist-based drugs in personalized cancer treatments may improve effectiveness, reduce side effects, and increase accessibility to more patients." (PMID 41228373, 2025). "Notably, the incorporation of TLR7/8 agonists into cancer vaccine platforms has yielded encouraging results in preclinical models and is advancing toward clinical application." (PMID 41228373, 2025). "Notably, TLR7/8 agonists have found utility as adjuvants in cancer immunotherapy due to their capacity to induce the production of IFN-Is, proinflammatory cytokines, chemokines, and the upregulation of costimulatory molecules through the MyD88 pathway." (PMID 38605368, 2024). "Once interacting with the TLR7 on the cancer cell surface, this synthetic TLR activator can lead to the release of cytokines and chemokines such as tumor necrosis factor-alpha (TNF-α), interleukin-12 (IL-12), and IL-6, thus creating DC activation and specific tumor immune response." (PMID 39204409, 2024). "In this specific context, stimulation of TA-pDCs with a TLR7 agonist appeared to be challenging, therefore a different approach leveraging the potential of pDCs might be more suitable for cancer immunotherapy." (PMID 39575246, 2024). "Thus, we investigated the utility of R848 (Resiquimod), an innate immune agonist of the TLR7/8 pathway that is commonly used in cancer immunotherapy, in enhancing the immune-stimulatory effects of CD40 agonism." (PMID 39033322, 2024). "This selectivity may be important for treatment of cancers with immune stimulants, since potent immune activators such as TLR7 agonists have failed in human clinical trials because their systemic activation of the immune system could not be tolerated." (PMID 38384467, 2024). "In addition to TLR3, TLR7 agonists also inhibit Treg cell function, and activate NK cells, promoting anti-cancer immune responses." (PMID 37936697, 2023). "Furthermore, TLR7 methylation appeared to be inversely related to mRNA expression levels in various cancers (P < 0.05)." (PMID 37362864, 2023). "Similarly, MBS8 (TLR7/8 agonist) demonstrated anti-cancer activity, leading to the elimination of tumors in syngeneic mouse models." (PMID 36890302, 2023). "According to the data, TLR7 expression may impact how cancer patients react to immune checkpoint therapy, which would help us understand how immunotherapy works to treat cancer better." (PMID 37362864, 2023). "Based on the levels of TLR7 expression, two subgroups of cancer cases were identified." (PMID 37362864, 2023). "Notably, TLR 7/8 agonists (TLR7/8a) have gained attention for their potential to augment the effectiveness of cancer immunotherapy by activating CD8+ T cells." (PMID 37766179, 2023). "Recently, there had some evidence that immune-related TLR7 expression was related to cancer." (PMID 37362864, 2023). "Potentially, not all cancers cause pDC hypofunction or cause it to various degrees, which would explain observations that some pDCs responded to signaling through TLR7/TLR8." (PMID 36768258, 2023). "In summary, TLR7 expression levels were significantly abnormal in different cancer types." (PMID 37362864, 2023). "Thus, systemic administrative TLR7 agonist is expected in terms of expanding applicable cancer types." (PMID 36793737, 2023). "This study looked into the role of human TLR7 expression in pan-cancer." (PMID 37362864, 2023). "Future biological research was required to elucidate and confirm the role of TLR7 in cancer." (PMID 37362864, 2023). "This study used multiple databases to analyze the expression and prognosis of TLR7 in pan-cancer." (PMID 37362864, 2023). "The first is TLR agonist, which has been developed to activate TLR3, TLR4, TLR5, TLR7 and TLR9, most of which is still in clinical trials, among which MPLA as a TLR4 agonist and imiquimod as a TLR7 agonist has been approved by FDA for infectious diseases or cancer." (PMID 36650562, 2023).
cancer (continued). "Interestingly, caveolin-1, GRP78, D2R, TLR7, and Src signaling pathways are important not only during cancer formation but also during JEV-mediated neurodegeneration." (PMID 36560690, 2022). "However, multiple studies testing this and other TLR7 agonists in the context of cancer vaccines in mice and humans indicate improved vaccine-driven responses." (PMID 35651800, 2022). "Thus, even though multiple studies have concluded that TLR7 agonists in combination with cancer vaccines are safe and supports antigen-specific responses, optimization of dosing and timing for this class of vaccine adjuvant appears necessary." (PMID 35651800, 2022). "TLR7 expression is moderate in pan-cancer, lower than that of TLR4." (PMID 35801728, 2022). "However, in cancer, pDC exhibit an impaired response to TLR7/9 activation and reduced IFN-α production, contributing to the establishment of an immunosuppressive TME." (PMID 36365103, 2022). "However, it is worth mentioning that TLR7 and TLR9 expression levels were negatively linked with cancer cell sensitivity to Irofulven, an alkylating agent, indicating that as TLR7 and TLR9 expression levels grew, the risk of Irofulven resistance increased." (PMID 35801728, 2022). "Interestingly, TLR7/8 agonists R848 reversed this miseducation effect of oxaliplatin on MDSCs and enhanced the cytotoxic effect on cancer cells." (PMID 35745800, 2022). "Furthermore, the laser-triggered disintegration of CuS led to the collapse of release polymer coupling TLR7/8 agonist modified with mannose that activated DCs, enhancing the infiltration of T lymphocytes against cancer through manifold pathways." (PMID 35745800, 2022). "As in the application to cancer, however, the transition from treating topical infectious conditions to chronic systemic infections has also been limited by narrow therapeutic indexes of systemically/orally administered TLR7/8 agonists." (PMID 34058283, 2021). "In this context, the use of TLR7/8as proved critical because, the presence of the GU-rich signature of viral RNAs37 alone is insufficient to activate this receptor and trigger significant apoptosis in cancer cells." (PMID 33658617, 2021). "Roche is currently developing orally available synthetic TLR7/8 agonists for advanced cancers." (PMID 34058283, 2021). "In addition to studies of TLR agonist combinations as vaccine adjuvants, other groups have focused on the potential of TLR7/8 ligands to synergize with other immunotherapy modalities for cancer treatment." (PMID 34058283, 2021). "The cell context-dependent adjuvant activity of TLR8 and TLR7/8 RNA ligands described here might be important for the future optimization of γδ T-cell based cancer immunotherapy." (PMID 34315922, 2021). "Our data identifying TLR7 as a modulator of the angiogenic response of NSCLC could enrich and complete the scenario of the effects of TLR7 agonists in NSCLC cancer." (PMID 33578955, 2021). "Overall, previous studies have shown that TLR7 indeed promotes immune cell infiltration, and TLR7 combined with ICB could markedly improve the clinical outcomes of many patients with cancer." (PMID 33982398, 2021). "TLR‐7/8a adjuvant systems have been shown to enhance CD8 T‐cell responses in cancer vaccination models, induce an influx of migratory DCs to the LN, and increase DC antigen uptake during vaccine responses, as well as increase antibody responses to HIV vaccines in non‐human primates." (PMID 33955657, 2021). "However, another mechanism of action of TLR7/8 agonists as anti-cancer vaccine adjuvants has been their indirect activation of T cells." (PMID 33558639, 2021). "Occasional large cancer cells also had cytoplasmic TLR7 staining." (PMID 31238894, 2019). "We therefore tested whether recombinant IFN-β could synergize with two other TLR agonists, Pam3CSK4 (TLR1/2) and CL264 (TLR7) in inducing NO production and macrophage-mediated cancer cell growth inhibition by BMDMs." (PMID 30450098, 2018).
cancer (continued). "Our group previously showed that injecting TLR7 agonists into murine tumors induced resident mMDSC to differentiate into tumoricidal M1-like macrophages (MACinflam) and led to the elimination of established cancers." (PMID 29632539, 2018). "Regarding the testing in cancer cell lines, we observed a considerable negative IC50 shift in terms of cell growth, in cancer cells carrying the TLR7 mutated gene, when compared to wild type cell lines." (PMID 29462934, 2018). "TLR7 was found overexpressed in the nuclear membrane and nuclei of cancer cells (a novel localization discovered) having higher levels in HPV-positive specimens, unlike TLR9 that showed reduced expression levels in HPV-positive samples compared to HPV-negative." (PMID 29854832, 2018). "TLR7 also showed altered localization depending on the cancer cell status: it was found with elevated levels in the plasma membrane of cancer-free cells compared to cancer cells, where this receptor was observed to have higher levels in the nuclear membrane and nuclei." (PMID 29854832, 2018). "Further research on the synthesis of currently available TLR7 agonists may not only shed light on their preclinical pharmacological properties, but also on cancer therapy in the clinical setting." (PMID 28620298, 2017). "Imiquimod (IMQ), a synthetic TLR7 agonist, has been reported to induce apoptosis via modulation of the expression of Bcl-2/Bax in cells of various cancer types, including renal cell carcinoma, intraepithelial neoplasia, squamous cell carcinoma and basal cell carcinoma." (PMID 28212561, 2017). "There was another discovery which demonstrated that TLR7 activation by imiquimod and resiquimod could induce apoptosis of cancer cells in an assay involving Annexin V-staining." (PMID 28620298, 2017). "Therefore, targeting TLR7 and modulating TLR7 signaling have emerged as a novel therapeutic approach for the prevention and treatment of cancer." (PMID 27588480, 2016). "TLR7/8 ligand microRNA in blood of cancer patients can be detected as circulating biomarker." (PMID 27336891, 2016). "However, the effect of TLR7 on Treg cell function in cancer immunosurveillance is still not well understood." (PMID 25593198, 2015). "Furthermore, a relation between TLR7 and cancer has been also lately described; indeed the receptor is highly expressed in cancer cells such as chronic lymphocytic leukemia cells, and it regulates the pancreatic carcinogenesis in humans and mice." (PMID 26007168, 2015). "However, these two studies provide interesting perspectives on TLR7/8 engagement in cancer treatment." (PMID 25866635, 2015). "A TLR7/8 agonist may improve cancer immunotherapy by inducing the differentiation of myeloid-derived suppressor cells, which accumulate in cancer patients and suppress the host immune system, into macrophages and dendritic cells." (PMID 25971982, 2015). "The TLR7 is a promising pharmaceutical target for the treatment of several diseases, including cancer and viral pathologies; a major obstacle for the development of novel compounds targeting this membrane protein is however the lack of an experimental three dimensional structure." (PMID 26007168, 2015). "The findings in this report support the utility of 852A or a TLR7/8 agonist like 3M-003 in the treatment of cancer or other conditions in which the activation of B cells may be desirable." (PMID 18652679, 2008). "Consequently, TLR7 agonists have been employed in cancer immunotherapy." (PMID 39346737, 2024). "However, the prognosis of patients with COVID-19 cancer, TLR7 expression, and its relationship to immune infiltration and pan-cancer clinical relevance were still unknown and warrant further investigation." (PMID 37362864, 2023). "TLR7 in this context could promote an immune suppressive microenvironment through the stimulation of proinflammatory factors and regulation of immunosuppressive molecules, which protect cancer cell from the T-cell-mediated antitumor immune response." (PMID 34209514, 2021).
cancer (continued). "Interestingly, this study also found that combining the TLR7 knockout with TLR3 and TLR9 knockouts lead to the spontaneous emergence of cancer in the triple-TLR-deficient mice, suggesting a role for TLR3 and 9 in cancer immuno-surveillance." (PMID 33202596, 2020). "Hence, the only TLR agonist approved for cancer therapy is the one targeting TLR7/8, imiquimod." (PMID 32012718, 2020). "In addition, excessive expression of TLR7 has been demonstrated in a variety of malignant tumors." (PMID 27588480, 2016). "Additionally, stimulation with R848 induced an ~60-fold increased gene expression of COX-2 in TLR7+ PANC1 cancer cells (12 h after stimulation) and an ~34-fold increased level in TLR8+ PANC1 cells (24 h after stimulation) compared with untreated cells (P<0.005 and 0.0001)." (PMID 26134824, 2015). "Recent studies have indicated an essential, yet dual role for TLR7 and TLR8 also in cancer progression and immune control." (PMID 40336011, 2025). "Several new adjuvants, including TLR3, TLR7, and TLR9 agonists, are undergoing clinical trials to enhance the efficacy of immune checkpoint inhibitors and improve cancer vaccine responses." (PMID 39206192, 2024). "•Scientific question: Toll-like receptor 7 (TLR7), a severe acute respiratory syndrome 2 (SARS-CoV-2) virus’s nucleic acid sensor, was discovered to be aberrantly expressed in many types of cancers." (PMID 37362864, 2023). "Toll-like receptor 7 (TLR7), a severe acute respiratory syndrome 2 (SARS-CoV-2) virus's nucleic acid sensor, was discovered to be aberrantly expressed in many types of cancers." (PMID 37362864, 2023). "While treating patients suffering from chronic hepatitis C virus (HCV) infection and cancer, ANA773- the orally administered TLR7/8 agonist, induced IFN-α, activated NK cells, and reduced serum HCV RNA levels." (PMID 37936697, 2023). "Toll-like receptor-7 (TLR-7) agonist, imiquimod, embedded in PLGA NPs is functionalized with the cancer cell membrane to expose the membrane proteins as antigens." (PMID 38112935, 2023). "Stimulation of TLR7/TLR8 expression resulted in elevated NF-κB and COX-2 expression and, more importantly, increased cancer cell proliferation and reduced chemosensitivity." (PMID 36476317, 2022). "The immune-based anti-cancer mechanisms of RSQ are similar to those of IMQ; however, RSQ has the advantage of being able to trigger both TLR-7 and TLR-8 signaling." (PMID 36297510, 2022). "TLR agonists approved by the FDA for the treatment in cancer patients include Bacillus Calmette-Guérin (BCG) (activates TLR2, TLR3, TLR4 and TLR9), monophosphoryl lipid (MPL) (TLR4 agonist) and imiquimod (TLR7 agonist)." (PMID 36365103, 2022). "TLR1, TLR2, TLR3, TLR4, and TLR5 expression levels were high across the six immune subtypes in the pan-cancer data; TLR6, TLR7, TLR8, and TLR10 expression levels were moderate; and TLR9, TLR12P, and TLR8-AS1 expression levels were extremely low." (PMID 35801728, 2022). "Meanwhile, many studies have revealed that the expression levels of TLR7 and TLR8 are altered in some autoimmune diseases, such as arthritis, cancers, or in antiviral regimes, including coronavirus and human immunodeficiency virus(HIV) prevention." (PMID 36476317, 2022). "Imiquimod is a Toll-like receptor 7 (TLR-7) activator, which can activate innate immune cells via TLR-7 or induce apoptosis and autophagy in cancer alone." (PMID 35754800, 2022). "Many studies have revealed that the expression levels of TLR7 and TLR8 are altered in some autoimmune diseases, such as arthritis, cancers, or in antiviral regimes, including corona virus prevention and HIV." (PMID 35452465, 2022). "FCGBP, FLNC, TLR7, and CSF2RA were potential antigens for developing cancer vaccination, and the patients in IS3 were considered the most suitable for vaccination in LGG." (PMID 34404444, 2021).